RNU6-345P (RNA, U6 small nuclear 345, pseudogene)
Gene: Small nuclear RNA gene on chromosome X (101,915,589 to 101,915,695, forward strand). Ensembl gene ENSG00000252810.
Homologues: Orthologues: chimpanzee U6 (99% identical), guinea pig U6 (85% identical). Paralogues in human: RNU6-1060P (89% identical), RNU6-116P (89% identical), RNU6-15P (89% identical), RNU6-266P (89% identical), RNU6-949P (89% identical), RNU6-1011P (88% identical), RNU6-1145P (88% identical), RNU6-151P (88% identical), RNU6-21P (88% identical), RNU6-29P (88% identical), RNU6-33P (88% identical), RNU6-38P (88% identical), and 1285 more.